IRF2BPL (interferon regulatory factor 2 binding protein like)
Description:
Probable E3 ubiquitin protein ligase involved in the proteasome-mediated ubiquitin-dependent degradation of target proteins. Through the degradation of CTNNB1, functions downstream of FOXF2 to negatively regulate the Wnt signaling pathway. Probably plays a role in the development of the central nervous system and in neuronal maintenance (Probable). Also acts as a transcriptional regulator of genes controlling female reproductive function. May play a role in gene transcription by transactivating GNRH1 promoter and repressing PENK promoter (By similarity).
Synonyms: C14orf4; EAP1; KIAA1865; NEDAMSS
Tractability: PROTAC: UniProt records ubiquitination sites on it; ubiquitination databases record sites on it; its protein half-life has been measured.
Gene: Protein-coding gene on chromosome 14 (77,024,543 to 77,028,708, reverse strand). Ensembl gene ENSG00000119669.
Subcellular location: Nucleus
Subcellular location (Human Protein Atlas): Nucleoplasm; Nuclear bodies
Gene Ontology:
Molecular function: protein binding; ubiquitin protein ligase activity
Biological process: negative regulation of transcription by RNA polymerase II; nervous system development; positive regulation of transcription by RNA polymerase II; development of secondary female sexual characteristics; protein ubiquitination
Cellular component: extracellular region; nuclear body; nucleoplasm; nucleus
Genetic constraint (gnomAD): Loss-of-function variants: 13 observed, 37.98 expected, observed/expected ratio (o/e) 0.34, 90% interval 0.22 to 0.54. The synonymous counts are far from expectation, so gnomAD's model fits this gene poorly and the ratio says little. Missense variants: 1,162 observed, 1,009.3 expected, observed/expected ratio (o/e) 1.15, 90% interval 1.1 to 1.21. Synonymous variants: 740 observed, 479.66 expected, observed/expected ratio (o/e) 1.54, 90% interval 1.45 to 1.64.
Gene-disease validity (ClinGen):
ClinGen rates the evidence that IRF2BPL causes each of these diseases.
neurodegenerative disease (autosomal dominant): Definitive. A disorder of the central nervous system characterized by gradual and progressive loss of neural tissue and neurologic function.
Homologues: Orthologues: rat Irf2bpl (96% identical), mouse Irf2bpl (95% identical), guinea pig IRF2BPL (94% identical), pig IRF2BPL (73% identical), rabbit IRF2BPL (70% identical), zebrafish irf2bpl (66% identical), tropical clawed frog irf2bpl (66% identical), Drosophila melanogaster Pits (26% identical), Caenorhabditis elegans ifbp-1 (19% identical), Caenorhabditis elegans ztf-11 (6% identical). Paralogues in human: IRF2BP2 (40% identical), IRF2BP1 (37% identical), MYT1 (16% identical), MYT1L (15% identical), ST18 (14% identical).
Diseases named in the same sentence as IRF2BPL in open-access papers:
IRF2BPL is named in the same sentence as 24 diseases in open-access papers, as found by Europe PMC text mining. Sharing a sentence is not in itself a finding about the gene and the disease. The quoted sentences say what the papers report.
Ataxia (4 papers, 2018 to 2024). Ataxia refers to impaired coordination of voluntary muscle movement. "Finally, a recent report from the UDN and MOSC has linked loss-of-function truncation mutations in the Interferon Regulatory Factor 2 Binding Protein Like (IRF2BPL) gene with a syndrome involving severe neurodevelopmental regression, hypotonia, ataxia, seizures, and lack of coordination." (PMID 30011838, 2018).
Dystonia (3 papers, 2021 to 2025). An abnormally increased muscular tone that causes fixed abnormal postures. "IRF2BPL as a transcriptional cofactor, is a new participant in the regulation of cell homeostasis, and also is a new genetic causes for disorders in dystonia." (PMID 34090334, 2021). "Additionally, likely pathogenic or pathogenic variants were found in ATP1A3 (n = 5) and GNAO1 (n = 1) for genes causing combined dystonia, as well as ACTB (n = 1), IRF2BPL (n = 1), SPR (n = 1), and TUBB4A (n = 3) for genes linked to dystonia with other neurological or systemic features." (PMID 40533913, 2025).
neurodevelopmental disorder with regression, abnormal movements, loss of speech, and seizures (3 papers, 2021 to 2025). "In humans, mutations in IRF2BPL lead to a neurodevelopmental disorder called NEDAMSS (Neurodevelopmental Disorder with Regression, Abnormal Movements, Loss of Speech, and Seizures; OMIM-#618088)." (PMID 38903604, 2024). "De novo truncations in the intronless gene interferon regulatory factor 2 binding protein-like (IRF2BPL) cause neurodevelopmental disorder with regression, abnormal movements, loss of speech, and seizures (NEDAMSS)." (PMID 40377402, 2025).
COVID-19 (1 paper, 2021). A disease caused by infection with severe acute respiratory syndrome coronavirus 2. "Eight ISGs were downregulated in Asymptomatic as compared with severe COVID-19 cases; CNP, CSF1, IRF1, IFITM10, IRF2BP2, IRF2BPL, SLC25A28 and SOCS3." (PMID 34824360, 2021). "Of these, nine ISGs were differentially regulated in Asymptomatic versus mild COVID-19 cases; IFNAR2, IRF2BP1, IRF4, MAVS, and TRIM14 were upregulated; whilst IRF2BP2, IRF2BPL, and SOCS3 were downregulated." (PMID 34824360, 2021).
depression (1 paper, 2024). "Alterations in IRF2BPL levels has been associated with neurological phenotypes and with major depressive disorder." (PMID 38493246, 2024).
developmental epileptic encephalopathy (1 paper, 2023). "Notably, de novo truncating variants in IRF2BPL are lately reported to cause developmental epileptic encephalopathy." (PMID 37501076, 2023).
osteoarthritis (1 paper, 2024). A noninflammatory degenerative joint disease occurring chiefly in older persons, characterized by degeneration of the articular cartilage, hypertrophy of bone at the margins and changes in the synovial membrane. "Another circRERE, formed by back-splicing of exons 5-8, is found to be reduced in osteoarthritis cartilage and is associated with increased apoptosis and abnormal β-catenin ubiquitination and degradation via the miR-195-5p/IRF2BPL axis." (PMID 39253079, 2024).
genetic disorder (2 papers, 2022 to 2025). "Similarly, NEDAMSS, a recently described genetic disorder linked to IRF2BPL variants and characterized by developmental regression, movement abnormalities, and profound speech loss with phenotypic overlap with our patient’s course but different genetic variants." (PMID 41040937, 2025).
tumor (2 papers, 2021 to 2022). "IRF2BPL is one of three members of a family of transcriptional regulators that potentially control various hallmarks of oncogenesis, including tumor suppression depending on the context." (PMID 36430209, 2022). "FOXF2 is a critical tumour suppressor in gastric carcinogenesis that mediates upregulation of the E3 ligase IRF2BPL to drive ubiquitylation and degradation of β-catenin, which blunts Wnt signalling and suppresses carcinogenesis." (PMID 34645493, 2021).
neurological disorders (1 paper, 2024). "In addition, other genes upregulated after finasteride treatment in the hypothalamus, like VGF and IRF2BPL, are associated with neurological disorders." (PMID 38493246, 2024).
IRF2BPL also shares sentences with these, for which no sentence is quoted: neurodevelopmental disorder (6 papers); epilepsy (3); developmental delay (2); Anxiety (1); autism (1); autism spectrum disorder (1); Brain atrophy (1); epileptic syndrome (1); HCMV infection (1); neurodegenerative disease (1); peripheral neuropathies (1); Primary hemophagocytic lymphohistiocytosis (1); Seizure (1); synovitis (1).